CCL2 (C-C motif chemokine ligand 2)
Diseases named in the same sentence as CCL2 in open-access papers (continued):
Sharing a sentence is not in itself a finding about the gene and the disease.
tumor (continued). "Tumor-derived CCL2 has also been shown to act directly on the endothelium to promote its activation, resulting in enhanced monocyte recruitment, dephosphorylation of VE-Cadherin, reduced tight junction integrity, and a consequential increase in tumor cell transmigration." (PMID 31497019, 2019). "In addition, tumor-infiltrating T cells, triggering by CCL2 produced by cancer cells, TAMs, and CAFs acquire CD4/CD25 expression and transform to Treg in TME." (PMID 31450710, 2019). "Additionally, CCL2, when engaged with CCR2 expressed on the recruited immature monocytes and triggering their maturation into tumor associated macrophages (TAM), has been reported to evoke IL6 secretion that activates STAT3-mediated signaling." (PMID 31861892, 2019). "Moreover, MSC-derived CCL2 has attracted macrophages to TNBC tumors, activating them to secrete CXCL8, thus leading to an overall increase in tumor-associated macrophages and endothelial cells." (PMID 31031757, 2019). "Based on these findings, treatment with anti-CCL2 antibody might sound attractive for tumor regression." (PMID 31474975, 2019). "Our in vitro results confirmed that CTRP1 might promote tumor progression by regulating CCL2 expression." (PMID 31183364, 2019). "Cathepsin K contributed to tumor macrophage recruitment via increased levels of chemokine CCL2." (PMID 31555270, 2019). "Moreover, additional precaution must be taken, as discontinuation of CCL2 therapy in murine models of breast cancer showed increased monocyte mobilization and tumor progression." (PMID 31547627, 2019). "Additionally, hypoxia can also promote TAMs to infiltrate in the inner region of the tumor by secreting chemokines such as chemokine C-C motif ligand 2 (CCL2), CCL5 and CSF-1." (PMID 31629410, 2019). "Together, these observations suggest that CCL2 is involved in tumor angiogenesis via macrophages." (PMID 31366997, 2019). "miRNA-1 and miRNA-206 were demonstrated to target vascular endothelial growth factor A (VEGFA) and chemokine (C-C motif) ligand 2 (CCL2), while miRNA-31 was found to target forkhead box O3 (FOXO3a, a tumour suppressor) that was suggested to inhibit VEGFA expression in fibroblasts." (PMID 30944831, 2019). "CCL2 was mainly present in the cytoplasm of the tumor cells in SACC tissues." (PMID 31024838, 2019). "In addition, CCL2, secreted by primary tumor cells, stimulates lung ECs to release S100A8 and S100A9, leading to paracrine upregulation of SAA3, and consequently the formation of the premetastatic niche." (PMID 30654796, 2019). "Since CCL2 was critical for myeloid cells accumulation in residual tumor, we assessed whether targeting myeloid cells with CCR2 antagonist (CCR2a) could inhibit the growth of the residual tumor." (PMID 31780645, 2019). "In addition, TGFβ signaling in bone marrow cells of BCC mice appears to support tumor growth by recruiting immunosuppressive myeloid derived suppressor cells (MDSC) to BCC lesions in a C-C motif chemokine ligand 2 (CCL2) dependent manner." (PMID 31878932, 2019). "Here we show accumulation of miR-375 in TAMs and assign a function to this miR as a regulator of MΦ migration by (a) identifying its target genes in TAMs and (b) describing a previously unknown function in tumor cells as a regulator of CCL2 expression." (PMID 30850595, 2019). "Macrophage chemoattractant chemokines MCP-1 (CCL2) and RANTES (CCL5): In a rat model of cancer and in human monocytes in vitro, Josephs and colleagues demonstrated, that IgE crosslinking triggered a TNFα/MCP-1 axis, which resulted in recruitment of macrophages into tumours." (PMID 30956175, 2019). "In tumor cells, miR-375 regulates CCL2 expression to increase recruitment of macrophages." (PMID 30850595, 2019). "However, when CCL2 pretreated tumor-naive neutrophils were seeded together with 67NR cells, the neutrophils were then cytotoxic." (PMID 31921102, 2019). "Furthermore, CCL2, which is produced by different tumor types, plays a critical role in tumor metastasis." (PMID 31448238, 2019).
tumor (continued). "Furthermore, we observed CCL2 knockout downregulated expression of the immunosuppression-related genes and attenuated the growth of the residual tumor." (PMID 31780645, 2019). "During tumor development and progression, circulating bone marrow-derived monocytes are recruited to the tumor by chemokine C-C motif ligand 2 (CCL2) and macrophage colony stimulating factor (M-CSF)-1 where they differentiate into TAMs with a M2-like phenotype." (PMID 31475003, 2019). "Interestingly, they observed a difference in the effects of tumor-derived CCL2 and recombinant CCL2, being that only the latter was able to induce IL-12 protein expression." (PMID 31921102, 2019). "c-Myb efficiently suppressed the inflammatory circuit including the Ccl2 chemokine in mouse models of BC and attenuated tumor dissemination suggesting that c-Myb-regulated transcriptional program may affect recruitment and/or activity of immune cells." (PMID 31406165, 2019). "Expression of Rgs2, an inhibitor of cell proliferation and mediator of cell differentiation, was shown to be highly upregulated in MDSCs from tumor-bearing mice, and knockout of Rgs2 led to decreased CCL2 expression and reduced tumor growth due to decreased vascularization in vivo." (PMID 31921102, 2019). "We have reported that TAM express more CCL2 than tumor cells." (PMID 30840689, 2019). "Furthermore, IHC confirmed that CCL2 was overexpressed in residual tumor cells adjacent to the necrotic zone with a large number of F4/80+ cell infiltration." (PMID 31780645, 2019). "Tumor-derived fibroblasts produce MCP-1 (CCL2) and RANTES (CCL5) could attract Th17 cells intensively." (PMID 31024835, 2019). "We established the tumor xenograft mice model with SACC-83 cells to investigate whether blocking the CCL2/CCR2 axis by the CCR2 antagonist could inhibit the development of SACC." (PMID 31024838, 2019). "CCL2 is highly expressed in malignant tumor cells and may play an essential role in TAM recruitment." (PMID 31781676, 2019). "Further, conditioned medium from MSCs exposed to tumor cell-derived extracellular vesicles (EVs) caused an upregulation in STAT3 phosphorylation and proliferation of CCA cells, possibly by secretion of CCL2/MCP1, CXCL1/GRO-α, CXC3CL1/Fractalkine, IL-6, and PDGF-AA." (PMID 31921870, 2019). "Furthermore, we confirmed that tumor cells-derived CCL2 is critical for the recruitment of monocytes and TAMs into tumors, which was consistent with the surgery-induced mobilization of myeloid cells." (PMID 31780645, 2019). "The expression of TNF-α, IL-1α, and IL-6 from MDA-MB-231 cells was shown to be inhibited by apigenin, and the inhibition of TNF-α-induced CCL2 release by apigenin was thought to suppress tumor migration and metastasis through the regulation of tumor microenvironment." (PMID 31252615, 2019). "Additionally, tumor secreted factors such as CCL2 can activate cells in the bone marrow promoting a premetastatic niche and paving the way for successful tumor dissemination at a secondary site." (PMID 30261690, 2018). "It has been demonstrated that CCL2 is crucial in promoting infiltration of MDSCs into tumor sites." (PMID 30619286, 2018). "Tumours can furthermore prevent the expression of T cell attractive chemokines such as CCL2, 3, 4, 5, 9 and 10, which may hinder trafficking of T cells to tumour beds." (PMID 30103501, 2018). "In addition, CCL2, which was upregulated in 231_HM.LNm5 tumour cells, can indirectly promote tumour angiogenesis via recruitment of macrophages." (PMID 29720474, 2018). "Furthermore, LNMAT1-induced upregulation of CCL2 recruits macrophages into the tumor, which promotes lymphatic metastasis via VEGF-C excretion." (PMID 30237493, 2018). "Thus, as for other chemokines, a big effort needs to be made to define the timing and dosage of CCL2-inhibition in tumor-bearing hosts." (PMID 30591657, 2018).
tumor (continued). "During cancer development, macrophages are recruited in the tumor stroma by several inflammatory mediators, such as chemokines: CCL2 (also known as MCP-1), CCL5, CXCL12 (also known as SDF-1), cytokines: vascular endothelial growth factor (VEGF), CSF1, and activated complement elements." (PMID 29675018, 2018). "We further tested whether increased IL-6 and CCL2 expression in tumor epithelial cells is a direct result of increased cellular stress in response to IGF-1R inhibition." (PMID 30458886, 2018). "Further research is required to determine whether CMV affects the recruitment of Treg into the tumor niche or the expression of CCL2/MCP-1 is the result of CMV-independent cancer mechanisms." (PMID 29467963, 2018). "Additionally, CCL2 is overexpressed in several malignant tumors, including MM-231-tumor xenograft for TNBC models." (PMID 30059519, 2018). "Approximately 50% of cases showed moderate to strong CCL2 staining despite the tumor subtypes." (PMID 29934505, 2018). "Furthermore, this appears to be ancestry-related, as SNPs in CCL2 and CCL5, which are associated with macrophage recruitment to the tumor, were associated with tumors of AA women and increased in AA QNBC patients." (PMID 29912871, 2018). "To obtain direct evidence of the role of macrophages for in vivo killing, we found that the use of a neutralizing mAb against the chemokine (C-C motif) ligand 2 (CCL2) resulted in a selective depletion of CD11b+F4/80+ cells within the tumor, and abrogated immunoprotection in TCR-Tg mice." (PMID 30083157, 2018). "Additionally, in several animal models of non–small-cell lung cancer (NSCLC) CCL2 blockade significantly reduced tumor growth." (PMID 30245686, 2018). "Interestingly, agents targeting tumor-associated macrophages such as the CCL2 inhibitor carlumab have had limited effect as single-agents and in fact may only have efficacy when combined with other agents such as RT that perturb the tumor immune microenvironment." (PMID 30692991, 2018). "Tumor-derived soluble mediators such as chemokines (CCL2, CCL5, CXCL12), colony-stimulating factor-1 (CSF-1), TGF-β, IL-10, prostaglandin E2 (PGE2) and metabolites (lactate) likely contribute to the development of TAMs with M2-like phenotype and tumor-promoting properties." (PMID 30563569, 2018). "Indeed, analysis of the relative proximity of dye-labeled, adoptively transferred, KLRG1+ NK cells from WT and Ackr2−/− mice to tumor deposits indicated that NK cells from Ackr2−/− mice migrated closer to CCL2-expressing tumors than WT cells." (PMID 30158126, 2018). "Besides direct effects of IL-1β and products of its target genes on the expansion of the MDSC pool, IL-1β induced CC-chemokine ligand 2 (CCL2) in macrophages and tumor cells." (PMID 30042333, 2018). "Additionally, through some of the same factors, plus others such as chemokine C-C motif ligand 2 (CCL-2) and fibroblast activation protein, CAFs recruit macrophages to the tumor environment, leading to immune suppression." (PMID 30487436, 2018). "Interestingly, work by Kang and Lu showed that ectopic expression of CCL2 in 231_LM2 cells enhanced experimental metastasis to lung via recruitment of tumour-promoting lung macrophages that display its cognate receptor CCR2." (PMID 29720474, 2018). "Gene expression in TAMs isolated from tumours treated with combination IR and aCSF revealed a general trend towards greater expression of pro‐inflammatory genes, with increases in iNOS, interleukin‐1A and B and a reduction in arginase, CCL2 and IL‐10." (PMID 30442705, 2018). "On the other hand, CCL2 or peripheral immune cell trafficking to the brain may play a role in the context of chemotherapy-induced behavioral changes, as CCL2 ablation improves 5-FU chemotherapy-induced fatigue in tumor-free mice." (PMID 29930550, 2018).
tumor (continued). "This evidence indicates that MDSCs block RT-induced T-cell anti-tumor activity via CCL2 and suggests this is a therapeutic target that could be manipulated to tip the balance in favor of dendritic cell recruitment." (PMID 30766539, 2018). "Tumor-derived miR-146a may induce the activation of Notch1 in BMSCs stimulating them to secrete CCL2 and several cytokines including IL-8, IL-6, CXCL1, IP-10, and CCL5 that enhance myeloma cell viability and migration." (PMID 30154786, 2018). "Importantly, IL-6 and CCL2 production in mouse and human tumor epithelial cells is elevated with reduced IGF-1R function." (PMID 30458886, 2018). "Interestingly, MITF knockdown also led to increased CCL-2 levels, which were involved in the tumor-promoting effect." (PMID 30237393, 2018). "Moreover, when an anti-CCL2 antibody was used to decrease macrophage infiltration in lung tumours, the tumour suppression mediated by HCQ was abolished as well." (PMID 30373678, 2018). "However, when the tumor cells were also stimulated with the type 1 cytokine IFNγ and TNFα an increased expression of CCL2, CCL5, CXCL9, CXCL10 and IL-6 was detected when compared to treatment with the control antibody." (PMID 30192802, 2018). "Downregulation of CCL2 was also reported to enhance tumor cell apoptosis and block the recruitment of inflammatory monocytes, inhibit lung metastasis of BC cells and prolong the survival of tumor-bearing mice and TNBC patients." (PMID 30059519, 2018). "Similarly, monoclonal antibodies against CCL2 led to tumor rejection in 40% of mice, but only when combined with RT." (PMID 30766539, 2018). "Importantly, a relevant issue that must be discussed in this regard is the pivotal role of CCL2 in early tumor immune-surveillance." (PMID 30591657, 2018). "The CCL2/CCR2 axis has been previously implicated in the metastatic process of several adult cancers and it likely plays a role in tumor cells transiting in and out of the blood circulation, through various mechanisms, probably including macrophage recruitment." (PMID 29584702, 2018). "These cells migrated to the tumor bed in response to CCL2 accumulation." (PMID 30420855, 2018). "CCL2 might be considered the main attractant for macrophages and MDSCs into the tumor microenvironment and triggers macrophage mediated angiogenic switch and MDSC-dependent suppression of antitumor immunity." (PMID 30591657, 2018). "CCL2 recruits monocytes with CCR2 from the peripheral blood to tumor site and interacts with them." (PMID 29458367, 2018). "The role of CCL2 in the development of tumor is mediated through its receptor CCR2." (PMID 29458367, 2018). "Thus, the regulation of FBW7 is expected to exhibit anti-metastatic function through the regulation of the interaction between Notch-1 and CCL2 in tumor stroma composed of F4/F80-positive TAMs and Ly6C-positive MDSCs." (PMID 30053872, 2018). "Furthermore, due to their high plasticity, they undergo changes within tumor microenvironment, following the release of CCL2 that is produced by tumor cells, TAMs, and CAFs." (PMID 30249019, 2018). "CCL2 is a pro-inflammatory chemokine that attracts monocytes to tumor sites." (PMID 29364159, 2018). "To this end, we previously established a 3D mono and co-culture model with lung, breast and pancreatic cancer cell lines and tumor-associated fibroblasts and identified soluble factors such as IL-6, CCL-2 and GM/M-CSF in co-culture supernatants that influence tumor growth and progression." (PMID 28750018, 2017). "The inhibition of CCL2 by an anti-CCL2 monoclonal antibody (e.g., carlumab) or through the inhibition of its synthesis (e.g., bindarit, trabectedin) prevented the recruitment of macrophages into the tumor site." (PMID 28769933, 2017). "Moreover, we know these tumor cells produce significant amounts of CCL2, even though they continue to express TGFβR2." (PMID 28143493, 2017).
tumor (continued). "Enhanced expression of the inflammatory chemokine CCL2 could also play a protective role against the tumor through the recruitment of type 1 cytotoxic γδ T lymphocytes to tumor beds." (PMID 29064427, 2017). "While we expected that the delivery of exogenous CCL2 might reduce the outgrowth of the tumor cells based upon Granot’s work, we observed the opposite, potentially because there was no significant increase in neutrophil recruitment the lung." (PMID 28143493, 2017). "Depending on whether CCL2 recruits pro-tumor or anti-tumor neutrophils and monocytes to the tumor will positively or negatively effect tumor growth." (PMID 28143493, 2017). "Moreover, tumor cells produce chemokines (such as chemokine C–C motif 2 (CCL2), -7 and -8) and cytokines, which attract inflammatory cells to the tumor site." (PMID 28471401, 2017). "Importantly, in vitro tumor cell migration and proliferation were not inhibited by the CCL-2 neutralizing antibody excluding any direct effects of the anti-CCL-2 antibody on tumor cell behavior." (PMID 28790339, 2017). "Another way to examine the impact of CCL2 expression by tumor cells is to determine whether CCL2 expression correlates positively or negatively with relapse free survival." (PMID 28143493, 2017). "TAMs are derived from peripheral blood monocytes and are recruited to the tumor area by various tumor-derived chemokines and cytokines such as colony stimulating factor-1 (CSF-1), C-C motif chemokine ligand 2 (CCL2), stromal cell-derived factor-1 (SDF-1), and VEGF-A." (PMID 28603525, 2017). "Similar to our finding upon depletion of macrophages, inhibition of macrophage recruitment to the biopsy-site using anti-CCL-2 neutralizing antibody resulted in a 3.25 (SD = 0.63) fold decrease in the number of migratory tumor cells compared to treatment with a control IgG antibody." (PMID 28790339, 2017). "Furthermore, IL6 and CCL2 are able to support tumor growth, EMT, stem cell migration, and finally treatment resistance." (PMID 29029509, 2017). "Other reports show that CCL2 production by tumor cells impairs T cell-mediated anti-tumor activity." (PMID 28143493, 2017). "CCL2 may attract anti-tumor immune cells that are required for efficient immunosurveillance, such that inhibition of CCL2 may promote neo-carcinogenesis as well as the development of metastases." (PMID 28143493, 2017). "Our results showed that l-CDL could downregulate tumor compression-induced CCL2 and CCR2 protein and mRNA expression in spinal cord showing that l-CDL could decline mechanical allodynia as well as microglial activation." (PMID 28587280, 2017). "Previous reports found a correlation of urinary CCL2 levels with tumor stage, grade and metastasis in patients with BCa, and patients with stages T2–T4 BCa were found to have a higher mean CCL2 concentration in their urine as compared to those with T1 stage tumors." (PMID 28757590, 2017). "MMTV-PyMT mice with a genetic deletion of either CCL2 or CCR2 exhibited earlier onset of tumor growth and increased metastasis, though the rate of primary tumor growth was enhanced, implying an anti-tumor role for CCL2 in early stages of tumor progression and in metastasis." (PMID 28143493, 2017). "However, the addition of CCL2 did increase tumor cell killing by the TENs in these co-cultures over that by the TENs alone (p = 0.005)." (PMID 28143493, 2017). "Indeed, tumor-produced nitrosylated CCL2, which is the main ligand for CCR2, has been shown to selectively recruit myeloid-derived suppressor cells (MDSCs) while abrogating recruitment of Th1 and cytotoxic T lymphocytes." (PMID 29020986, 2017). "Interestingly, IL-6, CCL2, and periostin were recently demonstrated to promote M2 macrophage polarization, and thus contribute to tumor growth." (PMID 28969635, 2017). "However, these processes are only consecutive to tumor-mediated immune reprogramming and activation in distant tissue and therefore dependent on CCL2/CCR2 driven S100A8/A9 release." (PMID 28744322, 2017).